DAZL (deleted in azoospermia like)
Diseases named in the same sentence as DAZL in open-access papers (continued):
Sharing a sentence is not in itself a finding about the gene and the disease.
seminoma (1 paper, 2023). A radiosensitive malignant germ cell tumor found in the testis (especially undescended), and extragonadal sites (anterior mediastinum and pineal gland). "Furthermore, seminomas have elevated levels of GDF3 expression compared to the normal testis, as well as other stem cell markers such as Nanog homeobox (NANOG) and octamer-binding transcription factor 4 (OCT4), and in particular DAZL (a germ cell-specific marker)." (PMID 37205315, 2023).
spermatogenic failure (1 paper, 2009). A male infertility characterized by dirsuption of the process of sperm development from diploid cells into mature haploid spermatozoa. "The A386G (T54A) polymorphism of the autosomal gene, DAZL, has shown susceptibility to spermatogenic failure in Taiwanese population." (PMID 19881148, 2009).
teratoma (1 paper, 2022). A non-seminomatous germ cell tumor characterized by the presence of various tissues which correspond to the different germinal layers (endoderm, mesoderm, and ectoderm). "In this study, we demonstrate that DAZL directly binds to pre-miRNAs and enhances the processing of pre-miRNAs to mature miRNAs, thereby reducing the proliferation of hPGCs and teratoma formation." (PMID 36273819, 2022). "Moreover, the overexpression of DAZL in NT2 cells clearly suppressed teratoma growth." (PMID 36273819, 2022).
testicular germ cell tumor (1 paper, 2022). A germ cell tumor arising from the testis. "Interestingly, one recent study identified a variant near the DAZL gene in one patient with a testicular germ cell tumor (TGCT), suggesting that a mutation causing abnormal expression of DAZL may lead to TGCT." (PMID 36273819, 2022).
tumor (7 papers, 2018 to 2023). "In this study, we further revealed that knockdown of DAZL greatly impaired germ cell formation and tumour initiation in U251, LN229 and A172 mut cells." (PMID 36435765, 2022). "If DAZL plays a role in regulating proliferation and pluripotency of human PGCs, it is more likely to participate in suppressing tumor formation." (PMID 36273819, 2022). "We then investigated the relationship between germ cell formation and tumour initiation by deleting DAZL, which plays a crucial role in germ cell development from PGC specification, PGC fate determination to PGC further mature, with CRISPR-Cas9 technology." (PMID 36435765, 2022). "To determine whether the inhibitory effect of DAZL on cell proliferation also occurs in other germ cell types, we overexpressed DAZL in a human testicular germline tumor cell line, NT2." (PMID 36273819, 2022). "Indeed, OCT4-positive tumor cells in both the kidney and pancreas often coexpressed DAZL, a late gonadal PGC marker." (PMID 34413299, 2021). "Moreover, DAZL inhibited germline tumor cell proliferation and teratoma formation." (PMID 36273819, 2022). "The established cell lines, with the expression of porcine SSC and germ cell markers UCHL1, PLZF, THY1, VASA and DAZL, could respond to retinoic acid (RA), and could colonize the recipient mouse testis without tumor formation after transplantation." (PMID 32308978, 2020).
cancer (5 papers, 2012 to 2024). A tumor composed of atypical neoplastic, often pleomorphic cells that invade other tissues. "DAZL is a cancer germline gene, which can promote tumor transformation, and plays important roles in cancer genesis and progression." (PMID 36672345, 2023). "We also identified the upregulation of DAZL and ANXA3 (data not shown), genes previously reported to be induced by 5-aza-dC, NDN, reported to be imprinted, and MT1G, reported to be methylated in other cancers." (PMID 22984426, 2012).
DAZL also shares sentences with these, for which no sentence is quoted: Premature ovarian insufficiency (2 papers); colorectal cancer (1); colorectal tumours (1); ovarian carcinoma (1); persistent fetal circulation syndrome (1); sarcoma (1); teratospermia (1).